NF1 (neurofibromin 1)
Diseases named in the same sentence as NF1 in open-access papers (continued):
Sharing a sentence is not in itself a finding about the gene and the disease.
autism (continued). "The similarities between the cognitive phenotypes of NF1 and idiopathic ASD make this single-gene disorder a relevant model of syndromic autism." (PMID 28932379, 2017). "Rather, the evidence for mTOR-signaling as a promising common ASD pathway candidate arise mostly from in vivo research into syndromic autisms such as Tuberous Sclerosis (TS), PTEN-related syndrome, Neurofibromatosis Type 1 (NF-1) and FXS." (PMID 28420080, 2017). "While these behaviours were relatively independent of other NF1 comorbidities, the importance of taking broader child characteristics into consideration when interpreting data from autism-specific measures in this population is highlighted." (PMID 34983638, 2022). "Lack of genetic validation of NF1, no clinical diagnosis of autism, and a retrospective assessment of autistic behaviours in early childhood." (PMID 34983638, 2022). "Trials have also not specifically targeted NF1-autism behavioural outcomes or used multiparametric imaging techniques." (PMID 29484149, 2018). "Regression of skills, which is a common feature in autism, was not reported in CFC but reported by 6.4% of parents in the NS group and 9.1% in the NF1 group." (PMID 33519543, 2020).
café-au-lait macules (43 papers, 2011 to 2025). "Like previous studies, the presence of café-au-lait macules was the most prominent of the diagnostic criteria for NF1, as shown in 83.12% of our patients." (PMID 37181996, 2023). "NF1 mutations lead to the dysfunction of the NF1 protein, resulting in café-au-lait spots, plexus neurofibroma, optic glioma, skeletal system disorders, and other manifestations." (PMID 36061378, 2022). "NF1 is caused by pathogenic variants in the NF1 gene on chromosome 17q11.2 and characterized by skin pigmentation anomalies such as café-au-lait macules (CALM) and skin-fold freckling, as well as dermal neurofibromas." (PMID 34928431, 2022). "NF1, caused by pathogenic variants in the NF1 gene, is characterized by café au lait macules, skin-fold freckling, Lisch nodules, optic glioma, and bone deformities." (PMID 32642740, 2020). "HiMels derived from café-au-lait macules have also been used to explore the role of neurofibromin 1 (NF1) in melanocyte differentiation." (PMID 38589876, 2024). "Caused by a germline heterozygous mutation in the tumor suppressor gene neurofibromin 1 (NF1; MIM: 613113) located on chromosome 17q11.2, NF1 is characterized by typical café-au-lait spots and cutaneous neurofibromas." (PMID 29914388, 2018). "In this study, the presence and number of skin manifestations related to NF1 (café-au-lait macules, cNF lesions, axillary/inguinal freckling) are monitored every 1–3 years." (PMID 29987133, 2018). "In the case of benign cNFs and café-au-lait macules, both highly penetrant lesions in NF1, neither Schwann cells nor melanocytes undergo malignant transformation, despite having biallelic mutations in the NF1 gene." (PMID 39687068, 2024).
gastrointestinal stromal tumor (42 papers, 2006 to 2026). "Despite a short median PFS, certain histological subtypes, including ASPS, chordomas, SMARCA4‐deficient tumors, gastro‐intestinal stromal tumor, and NF1 mutations, showed strong activity signals, indicating long‐term responses in some patients." (PMID 40911493, 2025). "Here, we present the first reported case of an unusual association of papillary thyroid carcinoma and gastrointestinal stromal tumor in a 30-year-old female patient who was previously diagnosed with NF1." (PMID 40708944, 2025). "Other malignant tumors strongly associated with NF1 include rhabdomyosarcoma, gastrointestinal stromal tumors, neuroectodermal tumors, pheochromocytomas, and breast carcinoma." (PMID 35490251, 2022). "•An association between Neurofibromatosis 1 (NF1) and gastrointestinal stromal tumors (GIST) has been reported in literature." (PMID 34274754, 2021). "Gastrointestinal stromal tumors (GISTs) are the most common mesenchymal neoplasms of the gastrointestinal tract and have also been described in association with NF1." (PMID 16640782, 2006). "NF1 is also associated with several tumors, including tumors of the nervous system (central and peripheral) and of the gastrointestinal (GI) tract, with the gastrointestinal stromal tumors (GISTs) indicated as the most common GI NF1-associated tumors." (PMID 24386562, 2013). "Patients affected by neurofibromatosis type 1 (NF-1), also known as von Recklinghausen disease, have an increased risk of developing gastrointestinal stromal tumors (GIST)." (PMID 38730658, 2024). "In patients with NF1, there is about a 45-fold increased risk for developing gastrointestinal stromal tumors (GIST) compared with sporadic GIST." (PMID 35490251, 2022). "The relevance of gastrointestinal stromal tumor (GIST) in NF1 is increasingly being reported in the literature and NF1-associated GIST has been identified to have an alternative molecular pathogenesis." (PMID 36701730, 2023). "The appearance of gastrointestinal stromal tumors (GISTs) and neuroendocrine tumors (NETs) surrounding the ampulla is regarded as an incredibly indicative and even pathological characteristic of NF1." (PMID 37773168, 2023). "It is expected that those carrying the NF1 gene will develop a rare mesenchymal tumor known as a gastrointestinal stromal tumor (GIST) more than general population." (PMID 36090331, 2022). "For gastrointestinal stromal tumor, the prevalence of the KIT mutation was similar between the two groups, but our cohort had a significantly higher prevalence of CDKN2A and NF1." (PMID 32373528, 2020). "KIT, PDGFRA, NF1 and SDH mutations are alternate initiating events, fostering hyperplasia in gastrointestinal stromal tumours (GISTs), and additional genetic alterations are required for progression to malignancy." (PMID 28270683, 2017). "The tumor spectrum in the NF1 probands included adenomatous polyps, two colonic adenocarcinomas, two gastrointestinal stromal tumors (GISTs), and one breast tumor." (PMID 21838856, 2011). "Notably, 30%–60% of NF1 patients may develop gastrointestinal stromal tumors (GIST), whose symptoms (e.g., bleeding) overlap with those of UC." (PMID 41346988, 2025). "About 10–15% of adult, and most pediatric, gastrointestinal stromal tumors (GIST) lack mutations in KIT, PDGFRA, SDHx, or RAS pathway components (KRAS, BRAF, NF1)." (PMID 27974047, 2016). "Recent studies have suggested that NF1 may also play a role in breast tumors, colorectal cancer, pancreatic ductal adenocarcinoma, gastrointestinal stromal tumor (GIST), and neoplasm of the bile duct." (PMID 37147639, 2023).
paraganglioma (41 papers, 2010 to 2025). A benign or malignant neoplasm arising from paraganglia located along the sympathetic or parasympathetic nerves. "Sporadic panNETs arose in 141 patients with panNET-associated familial syndromes in 42 individuals: 36 with MEN1, 2 with VHL, 1 each with TSC, NF1, paraganglioma, MAX mutation and MUTYH-associated polyposis." (PMID 34163434, 2021). "Moreover, three patients of G5 clinical group showed malignant pheochromocytoma/paragangliomas associated to NF1 and carried three different nonsense mutations (p.Arg1276*, p.Trp1641*, and p.Asn2364*) in the NF1, distributed in different protein domains." (PMID 35885913, 2022). "Additionally, in several recorded cases, paragangliomas violated the “mutual exclusion of mutations” rule: these tumors simultaneously carried somatic mutations in the NF1 gene and in the RET or VHL genes." (PMID 28187001, 2017). "Mutations in the VHL and NF1 genes are also associated with inherited paragangliomas." (PMID 20205783, 2010). "Most cases of hereditary paraganglioma are accounted for by pathogenic variants in SDHD, SDHB, and SDHC, VHL, and NF1." (PMID 38003974, 2023). "Fusion genes involving MAML3 (5%), BRAF (0.6%), NGFR (0.6%), and NF1 (0.6%) have been described as genetic disease drivers in a subset of paragangliomas." (PMID 32926213, 2020). "Mutations in RET, NF1 (neurofibromatosis 1), VHL (the von Hippel-Lindau) and SDH genes are frequent in paragangliomas which are neuroendocrine tumors." (PMID 24202337, 2013). "In a study that included 809 paragangliomas in the area of the head and neck, no mutation in the NF1 gene was identified." (PMID 39649680, 2024). "In addition, susceptibility to pheochromocytomas and paragangliomas is established in multiple endocrine neoplasia types 2A and 2B (MEN2), neurofibromatosis type 1 (NF1), von Hippel Lindau (VHL) disease, and the Carney–Stratakis dyad." (PMID 38003974, 2023). "Germline mutations have been identified in paragangliomas involving the proto-oncogene RET, tumor suppressor genes VHL, and NF1 The commonest clinical presentation is hypertension but incidentally detected forms have been reported during imaging and on a few occasions the diagnosis was missed." (PMID 36591002, 2022). "Functioning SDHx paragangliomas sometimes release dopamine and/or norepinephrine, originating raised plasma levels of methoxytyramine, contributing to distinguish SDHx patients from those with VHL, RET, or NF1 mutations." (PMID 24899893, 2014). "We could not include other paraganglioma genes like SDHA, SDHC, MAX, etc., and we did not include NF1 carrier cases in this study." (PMID 33777662, 2021).
von Hippel-Lindau disease (41 papers, 2005 to 2025). An autosomal dominant disorder caused by pathogenic variants in the VHL gene, leading to an increased risk of various benign and malignant tumors, including hemangioblastomas, retinal hemangiomas, endolymphatic sac tumors, renal cell carcinoma, and pheochromocytomas. "Other inherited syndromes associated with PanNETs include MEN4, von Hippel–Lindau (VHL) syndrome, neurofibromatosis type 1 (NF1), and tuberous sclerosis complex (TSC)." (PMID 38893191, 2024). "It is recognized that CP can be associated with genetic disorders such as NF1, von Hippel–Lindau disease, and multiple endocrine neoplasia." (PMID 36187102, 2022). "Additionally, five patients had mutations detected in the tumor suggesting a cancer predisposition syndrome (Von Hippel Lindau syndrome, Gorlin syndrome, NF1 and NF2, and CMMRD), which were then confirmed in the germline." (PMID 31827999, 2019). "While the presentation of chromaffin cell tumors has been well described with multiple endocrine neoplasia, NF1, and Von Hippel–Lindau syndromes, the identification of new gene mutations leading to chromaffin cell tumors at a young age is changing the landscape of how clinicians approach such cases." (PMID 28752085, 2017). "Hereditary syndromes linked to PCCs and PGLs are von Hippel-Lindau disease (VHL), neurofibromatosis type 1 (NF-1), and multiple endocrine neoplasia, especially type 2 (MEN 2); however, a non-negligible number of PCCs and PGLs are non-functioning, and most of them are sporadic." (PMID 36836029, 2023). "These include Multiple Endocrine Neoplasia type 1 (MEN1) (Wermer syndrome), von Hippel–Lindau disease, neurofibromatosis 1 (NF-1) and the tuberous sclerosis complex (TSC)." (PMID 36765737, 2023). "The adjusted HR varied from 22.4 (95% CI, 8.4-59.7) among individuals with von Hippel-Lindau disease to 31.3 (95% CI, 26.5-36.9) in NF1." (PMID 37490289, 2023). "These can be mainly found in clinical syndromes including multiple endocrine neoplasia (MEN), von Hippel–Lindau (VHL) syndrome, neurofibromatosis-1 (NF-1) and familial paraganglioma (FPGL)." (PMID 30613466, 2018). "Familial predisposition is seen mainly in patients with Multiple Endocrine Neoplasia (MEN) type 2, NF-1, von Hippel-Lindau disease and familial carotid body tumors." (PMID 20219130, 2010). "NENs, particularly well-differentiated, slow-growing tumors (NETs), can also occur in the context of hereditary syndromes, including multiple endocrine neoplasia type 1 (MEN1), von Hippel–Lindau syndrome (VHL), and neurofibromatosis 1 (NF-1), which is often linked to PanNETs." (PMID 41375037, 2025). "Neuroendocrine tumors also known as carcinoid tumors, most commonly occur sporadically but may be associated with hereditary syndromes such as multiple endocrine neoplasia type 1 (MEN1), neurofibromatosis type 1 (NF1), von Hippel–Lindau disease (VHL), and, more rarely, tuberous sclerosis." (PMID 40869648, 2025). "PCC occurs sporadically or within hereditary syndromes like von Hippel-Lindau disease (VHL), multiple endocrine neoplasia type 2 (MEN2), or neurofibromatosis type 1 (NF1), with mutations, particularly SDHB, increasing malignancy risk." (PMID 40927285, 2025). "Also, 9% of the cases are associated with Von Hippel-Lindau syndrome - VHL (VHL gene), 5% corresponds to multiple endocrine neoplasia 2 syndrome—MEN2 (RET proto-oncogene), and 2% are associated with neurofibromatosis type 1 syndrome—NF1 (NF1 gene)." (PMID 36685941, 2022). "While most pNETs are sporadic, some are associated with genetic syndromes such as Multiple Endocrine Neoplasia type 1 (MEN1), Von Hippel-Lindau disease [VHL), neurofibromatosis 1 (NF1), or tuberous sclerosis complex." (PMID 32947997, 2020). "Other well-known hereditary syndromes associated with PGL/PCC include multiple endocrine neoplasm type 2 (MEN2), von Hippel-Lindau disease (VHL) and neurofibromatosis type 1 (NF1)." (PMID 33308260, 2020).
von Hippel-Lindau disease (continued). "Associations with familial genetic syndromes such as multiple endocrine neoplasia type 1 (MEN1), von Hippel–Lindau syndrome (VHL), and neurofibromatosis-1 (NF1) have been described." (PMID 29899320, 2018). "Pancreatic NETs (PNETs) sometimes occur in hereditary diseases, such as multiple endocrine neoplasia type 1 (MEN-1) and von Hippel-Lindau disease (VHL), but they rarely develop in patients with NF-1." (PMID 22824559, 2012). "Key syndromes include multiple endocrine neoplasia type 1 (MEN1), von Hippel–Lindau disease (VHL), neurofibromatosis type 1 (NF1), and tuberous sclerosis complex (TSC), which are characterized by germline mutations in the tumor-suppressor genes MEN1, VHL, NF1, and TSC1 or TSC2, respectively." (PMID 32850899, 2020).
colorectal cancer (38 papers, 1994 to 2025). A primary or metastatic malignant neoplasm that affects the colon or rectum. "NF1 mutations were reported as potential biomarkers for poor prognosis in pancreatic ductal adenocarcinoma, colorectal cancer." (PMID 35702826, 2023). "Since NF1 is frequently co-mutated in KRAS G13-mutated colorectal cancer, these tumor cells can respond to EGFR inhibitors in an NF1-dependent manner." (PMID 34680229, 2021). "Additionally, low NF1 expression was also associated with poor prognosis in colorectal cancer patients." (PMID 37147639, 2023). "It is unclear whether this colorectal carcinoma is related to the NF1 mutation or whether it is a sporadic carcinoma." (PMID 28835241, 2017). "Colorectal carcinomas have been previously noted as a cause of death in NF1." (PMID 23244495, 2012). "Next generation sequencing studies identified that the NF1 gene is altered in approximately 5-6% of colorectal carcinomas." (PMID 30858928, 2019). "In contrast, NF1 was found to be altered in approximately 3.8-5.6% of colorectal carcinomas in two recent next generation sequencing studies." (PMID 25026295, 2014). "NF1-mutant colorectal cancer cell lines are resistant to EGFR inhibitors, indicating that loss of NF-1 could be a biomarker for assessing the application of EGFR inhibitors." (PMID 38084101, 2023). "Among the patients diagnosed as a diffuse IGNM associated with NF1, somatic mutations in NF1 gene related with RAS pathway may be implicated in the development of colorectal cancer." (PMID 35927360, 2022). "The presence of APC mutations as an alternative to CTNNB1 mutations in some POLE‐mutant endometrial cancers is an exemplar, and there are likely to be others, such as NF1 and RB1 mutations in endometrial cancer and atypical (Q61P, K117 N, and A146T) KRAS mutations in colorectal cancer." (PMID 29604063, 2018). "A final missense mutation (p.Phe894Cys) in Neurofibromin 1 (NF1), a tumor suppressor gene and a negative regulator of NRAS, is predicted pathogenic by SIFT/PolyPhen-2 and has been reported in association with one colorectal cancer by TCGA." (PMID 29254223, 2017). "Data on the nature and the frequency of NF1 aberrations in colorectal carcinoma vary widely." (PMID 25026295, 2014). "Seventeen colorectal cancers harboring a V600E mutation also presented with additional, predicted pathogenic mutations in KRAS, NRAS, or NF1 (17/709, 2.40%), comprising 13 colorectal cancers with NF1-inactivating mutations and four with KRAS mutations (4/709, 0.71%, mostly G12D)." (PMID 39751654, 2025). "Apart from a few Japanese reports, no other reports in the worldwide literature have mentioned a NF1 patient with both GIST and colorectal carcinoma." (PMID 28835241, 2017). "Most cancers with atypical KRAS mutations (291/335, 86.9%) had no additional mutations in BRAF, NRAS, or NF1, with the incidence of these mutations being far lower than the incidence of concomitant Ras mutations in atypical BRAF colorectal cancers." (PMID 39751654, 2025). "Of the 335 colorectal cancers, 13 (3.88%) with atypical KRAS also carried a typical KRAS mutation, and none of those tumors had an additional BRAF, NRAS, or NF1 mutation." (PMID 39751654, 2025). "Class 2–mutant and class 3–mutant colorectal cancers frequently co-occurred with additional Ras pathway mutations (29.0% and 45.7%, respectively, vs. 2.40% in class 1; P < 0.001), often at atypical sites (KRAS noncodon 12/13/61, NRAS, or NF1)." (PMID 39751654, 2025).